YBX1 (Y-box binding protein 1)
Diseases named in the same sentence as YBX1 in open-access papers (continued):
Sharing a sentence is not in itself a finding about the gene and the disease.
cancer (continued). "Our finding highlights that targeting the FGD5-AS1/YBX1 axis might be a promising anti-cancer strategy for GC." (PMID 38965605, 2024). "DSCAM-AS1 could promote cancer progression by interacting with YBX1 and regulating expression of FOXA1 and ERα." (PMID 38643469, 2024). "Furthermore, recent research indicates that TAS0612 and ipomus targeting the m5C ‘reader’ YBX1 have been demonstrated to diminish drug resistance in cancer therapy." (PMID 38572667, 2024). "Given YBX1’s role in immunity and inflammation, it is compelling to investigate the relationship between YBX1 and the tumor microbiome and, ultimately, how their interplay affects cancer progression." (PMID 38255791, 2024). "YBX1 can also be acetylated in pathological states or in cancers." (PMID 39727969, 2024). "Therefore, cancers with high expression of YBX1 provide a potential opportunity for cancer therapeutic intervention using conditionally replicating adenoviruses." (PMID 38255791, 2024). "YBX1 is highly expressed in many cancers and involved in numerous key cellular pathways." (PMID 36964534, 2023). "In particular, upregulation of ILF2 and YBX1 has been observed in a growing number of cancers." (PMID 36717549, 2023). "In cancer cells and preadipocytes, YBX1 knockdown reduces LC3 protein expression." (PMID 37965572, 2023). "In CRC, targeting YBX1 phosphorylation might inhibit NF-κB activity in cancer, thereby regulating CRC cell growth." (PMID 37504265, 2023). "YBX1 is necessary for cancer cell proliferation and embryonic development." (PMID 37965572, 2023). "Here we found AR expression in RCC cells decreased in response to hypoxia, which might then lead to increase the cancer stem cells (CSC) phenotype through the lncTCFL5-2-modulated YBX1/SOX2 signals." (PMID 36397101, 2022). "YBX1 inhibition might contribute to reduction of cancer progression, antagonism of treatment resistance, and decrease of OC patient mortality." (PMID 36545327, 2022). "YBX1 has been reported to promote the progression of many kinds of cancers." (PMID 36169095, 2022). "YBX1 acts as a reader to promote many kinds of cancers that have been reported." (PMID 36169095, 2022). "Similarly, IHC staining analysis revealed that YBX1 was elevated in TNBC tissues compared with adjacent non-cancer tissues." (PMID 34991621, 2022). "In addition, the m5C “reader” Y-box-binding-protein 1 (YBX1) is highly expressed in certain cisplatin-resistant cancers." (PMID 35721510, 2022). "YBX1 was expressed in diverse cancers and stabilized various oncogenic transcripts." (PMID 36072340, 2022). "Y-box binding protein-1 (YB-1) is a Csp upregulated in cancer cells." (PMID 36009571, 2022). "TP53TG1 binds to RNA-binding protein YBX1 to block its function and acts as an anti-cancer agent." (PMID 36267418, 2022). "Furthermore, YBX1 was found to be up-regulated in a variety of human cancers by analyzing GEPIA database." (PMID 33976741, 2021). "YBX1 acts as an oncoprotein in a variety of human cancers, but its role in NPC remains elusive." (PMID 33976741, 2021). "YBX1 is thus thought to be a master regulator of RNA regulated cancer cell biology." (PMID 34266873, 2021). "Similarly, IHC staining revealed that YBX1 was highly expressed in CRC tissues compared with the adjacent non-cancer tissues." (PMID 34079797, 2021). "YBX-1 is an RNA-binding protein that plays very important roles in tumorigenesis, development, metastasis, cancer treatment and drug resistance prediction and is abnormally expressed in various cancers." (PMID 34341710, 2021). "For example, YBX1, a DNA/RNA binding protein containing a cold-shock domain, server as an oncoprotein that regulates cell proliferation, survival, drug resistance, and chromatin instability in human cancers." (PMID 33976741, 2021).
cancer (continued). "Our mechanistic characterization of HOTAIR and its functional crosstalk with the well-established oncogene YBX1 may additionally serve to facilitate the development of cancer therapies targeting YBX1 through its interaction with HOTAIR." (PMID 34266873, 2021). "More recently, another report showed that in cancer cells NSUN2 aberrant methylation of oncogenic mRNAs at the 3′ UTR increased their interaction with the reader protein Y-box-binding protein 1 (YBX1), which maintained the stability of its targeted mRNAs by recruiting ELAVL1." (PMID 33461542, 2021). "LncRNA DSCAM-AS1 can interacts with YBX1 to facilitate cancer progression." (PMID 34395290, 2021). "DHX8, EIF3G, RBM22, U2AF1 UPF1 and YBX-1 are also candidates therapeutic targets for cancer therapy because the tumor cell progression was strongly inhibited by the downregulation of these RBPs in cancer cells, including HCT116, SUIT2 and OE33 cells, but not in non-cancerous cells." (PMID 34202873, 2021). "Under hypoxic stress, cancer cells could produce more tRFs that can compete with oncogene transcripts and then bind to YBX1, thereby promoting mRNA degradation and eventually inhibiting the proliferation of cancer cells." (PMID 33391486, 2021). "We could conclude that, firstly, it seems YBX1 more specifically regulates the first exon, as the splicing type is AT type in both studies; secondly, YBX1, as the hub SF, might regulate specific genes in different cancer types." (PMID 33101358, 2020). "Nuclear localization of YBX1 correlates with poor prognosis in many cancers including PCa." (PMID 32178290, 2020). "Both PRMT5 and YBX1 serve as a potential therapeutic target for cancer treatment." (PMID 33375283, 2020). "Y-box binding protein-1 (YB-1) is capable of mediating the chemoresistance of cancer cells." (PMID 32545648, 2020). "YBX1 acts as a cancer-promoting gene in a variety of cancers." (PMID 33144579, 2020). "Additionally, S102 is a widely studied residue on YBX1 that is subjected to phosphorylation, and it determines the subcellular localization of YBX1 and has crucial implications for the clinical outcome of different cancers." (PMID 33375283, 2020). "However, Ybx1 has been mostly studied in cancer cell lines, and the physiological role of Ybx1 in brain development is relatively less understood." (PMID 32792512, 2020). "Y-box binding protein 1 (YB-1), a member of the cold-shock protein superfamily encoded by YBX1 gene, is drastically increased in several types of cancer and it controls numerous cellular processes including DNA repair, transcription and translation of proteins." (PMID 32041631, 2020). "Y-box binding protein-1 has been shown to be important in other cancer CSCs as well." (PMID 31632972, 2019). "tRFs also competed for the mRNA binding sites of YBX1 to suppress cancer progression." (PMID 31746776, 2019). "The Y-box binding protein (YBX1) is known to be a multifunctional transcription and translation factor regulating protein expression; its aberrant activation thus influences various malignant phenotypes of cancer cells." (PMID 31495785, 2019). "YBX1 is also reported to regulate the expression of MAPK1, involved in cell proliferation and invasion, and CD44 and CD49f (or integrin alpha 6), the genes linked to cancer stem cells." (PMID 31358880, 2019). "In addition, RSK2 has a prominent role in the activation of the transcription factor Y-box binding protein-1 (YB-1) which is a main factor leading to the development of basal-like cancer." (PMID 31382504, 2019). "Y-box binding protein-1 (YB-1), an oncogenic transcription or translation factor, was identified as a marker of malignant cell transformation and tumor aggressiveness and as a potential molecular target for cancer therapy." (PMID 31624470, 2019). "Y-box binding protein 1 (YB-1) is an RNA and DNA binding factor with potential prognostic cancer." (PMID 28515422, 2017). "YBX-1 can promote GC development in both cancer cells and cancer vascular cells." (PMID 26805816, 2016).
cancer (continued). "Our current study has great significance by linking two well-known cancer culprits: NF-κB and YBX1." (PMID 26318844, 2015). "Thus, we provided a novel mechanism for the regulation of YBX1, which can be used as a potential strategy to control YBX1 and further lead to down-regulation of the activity of NF-κB in cancer." (PMID 26318844, 2015). "Since YBX1 is a tumor promoter, we wanted to examine whether YBX1 functions as a NF-κB activator in cancer cells." (PMID 26318844, 2015). "In addition, further phage-peptide clones with homology to YBX1, RPL15 and CHRNA2 have been associated with cancer and other disease." (PMID 26039628, 2015). "Since NF-κB is frequently activated in cancer, we would like to examine whether YBX1 is an activator of NF-κB and whether phosphorylation of S165 plays a critical role in this process." (PMID 26318844, 2015). "The Y-box binding protein 1 (YB-1) possesses pleiotropic functions through its interactions with various cellular proteins, and its high expression levels make it a potential useful prognostic biomarker for cancer cells." (PMID 25539742, 2014). "We used an approach for dynamic proteomics to measure the protein levels of PRC1 (protein regulator of cytokinesis 1, NM_003981), ANLN (anillin, NM_018685) and YB1 (Y-box binding protein-1, NM_004559) in individual living human cancer cells over several cell cycles." (PMID 19381343, 2009). "Thus, YBX1 has emerged as a potential therapeutic target for various types of cancer." (PMID 41507134, 2026). "Therefore, targeting specific lncRNAs could selectively affect the function of YBX1 in certain tumor tissues, suggesting an approach for cancer target therapy." (PMID 38899362, 2024). "Moreover, interventions aimed at disrupting YBX1-mediated integrin signaling could sever the essential link between cancer cells and the ECM, potentially halting malignancy progression." (PMID 38255791, 2024). "Thus, YBX1 may be a useful therapeutic target in cancer therapy to regulate tumorigenic SASP factors." (PMID 38003589, 2023). "In addition to the regulation of tumor proliferation, YBX1 could protect cancer cells against apoptosis." (PMID 36805592, 2023). "Moreover, YBX1 has also been reported to interact with multiple distinct oncogenic ncRNAs including lncRNAs, thereby regulating cancer progression and oncogene expression." (PMID 34266873, 2021). "Taken together, the SCAT7/hnRNPK/YBX1 RNP complex plays a crucial role in carcinogenesis, and SCAT7 may be used as a prognostic marker in risk assessments as well as potential therapeutic regimens in the treatment of cancer." (PMID 30658384, 2019). "Moreover, YBX1 is highly overexpressed in multiple cancer types and may serve as a potential prognostic marker for poor outcomes and drug resistance in specific cancer types." (PMID 28872613, 2017). "Therefore, our data, as a proof of principle, reveal a novel function of YBX1 in cancer metabolism." (PMID 29029484, 2017). "Hypoxia is responsible for activating ILK–AKT–Y box-binding protein 1 (YB-1), leading to the inhibition of FOXO3A and activation of epithelial–mesenchymal transition markers (ZEB1, Twist) and expression of biomarkers associated with cancer stem cell signaling pathways." (PMID 26425674, 2015). "Y-box binding protein 1 (YBX1) plays a crucial regulatory role in the development and progression of various cancers." (PMID 41507134, 2026). "YBX1 was also found in the IP/MS results from HEK293T cells, although with significantly lower abundance than in cancer cells." (PMID 41482854, 2026). "HOTAIR specifically binds to YBX1, promoting PI3K/Akt and ERK/RSK signaling pathways in cancer cells." (PMID 40799245, 2025). "DSCAM-AS1 forms a positive feedback loop with YBX1, activating FOXA1 transcriptional network to drive cancer progression." (PMID 40799245, 2025).
cancer (continued). "Overexpression of HCP5 stabilizes ferroptosis-related genes via the HCP5-132aa/YBX1/ELAVL1 ternary complex, suppressing ferroptosis and accelerating cancer progression." (PMID 41304936, 2025). "Among the ITAFs, some have been shown to play a significant role in stress response, cancer progression, and therapy resistance, including PTB (Polypyrimidine Tract Binding protein), hnRNP A1 and C1/C2, La autoantigen, and Y-box binding protein 1 (YB-1)." (PMID 40940829, 2025). "In cancer, GAS5 functions through mechanisms such as c-Myc translation repression, YBX1/p21 pathway regulation, and EZH2 suppression, providing cellular protection in each context." (PMID 39941145, 2025). "Future research should focus on further elucidating the precise mechanisms by which SOX12 and YBX1 regulate LDHA and exploring the potential of the targeting of this axis in other cancer types." (PMID 40593465, 2025). "The DNA/RNA-binding protein, Y-box binding protein 1 (YBX1), a well-known oncogene, is hyperactivated in nearly all cancer types." (PMID 40812419, 2025). "It is even more interesting to establish if, once nuclear, YBX1 in turn promotes HOTAIR induction, imposing additional advantage to invasive cancer cells." (PMID 40855961, 2025). "Here, we uncover a previously undescribed mechanism by which YBX1 regulates PDHA1 activity and the role of the YBX1–PDHA1 axis in cancer cells." (PMID 40812419, 2025). "Immunity-related GTPase M (IRGM), a critical player in immune regulation, interacts with YBX1 to facilitate PD-L1 transcription, suppressing CD8+ T cell infiltration in HCC and contributing to cancer progression." (PMID 38255791, 2024). "In particular, APE1 promotes YBX1 dual-phosphorylation at S174 and S176 by modulating PPP1R12A and PLK1 to enhance SG formation and cancer cell survival." (PMID 38436697, 2024). "The study showed that the binding of CAR10 with Y-box-binding protein 1 (YB-1) stabilizes the transcription factor, resulting in the increased expression of EGFR, enhancing cancer growth." (PMID 40176927, 2024). "In these cancers, DSCAM‐AS1 modulates the expression of FOXA1 and ERα by interacting with YBX1, influencing YBX1 recruitment to the promoter regions of FOXA1 and Erα and thereby promoting tumour progression." (PMID 39690143, 2024). "This study examined the clinical features expression, prognostic value, mutations, along with methylation patterns of three genes from the YBX family (YBX1, YBX2, and YBX3) in 28 different types of cancer." (PMID 38698857, 2024). "YBX1’s influence on these pathways dictates the cellular response to the ECM, influencing the invasive behavior of cancer cells towards metastasis." (PMID 38255791, 2024). "FBL’s influence on YBX1 enhances BRCA1 expression, revealing potential therapeutic targets to combat chemoresistance in cancer by understanding their interaction in DNA damage responses." (PMID 38255791, 2024). "A recent study reported that LRRC8A was upregulated by NSUN2-mediated m5C modification in cancer cells, and m5C-modified LRRC8A mRNA increased RNA stability by binding to YBX1." (PMID 39273558, 2024). "Y-Box-binding protein 1 (YBX-1) is an interaction partner of HUR, which is also overexpressed in many cancers and plays an important role in various cellular functions." (PMID 36918912, 2023). "This subtype-specific function of YBX1 is PI3K-dependent and underscores a pivotal role for YBX1 in fine-tuning the cancer cell fitness with a critical impact on HNC patient outcomes." (PMID 36949044, 2023). "We further identify YBX1 phosphorylation, downstream of the PI3K/mTOR pathway, restraining basal-like cancer cell proliferation." (PMID 36949044, 2023). "The other hub genes (e.g., YBX1, OLA1, TRMT10C, and KIF20A) also play a key role in the development and prognosis of the pan-cancer section." (PMID 35720008, 2022).
cancer (continued). "In sarcomas, YBX1 increases the translation of the RNA-binding protein G3BP1, which, via LLPS, initiates stress granule formation that enables cancer cells to sustain stress." (PMID 35406602, 2022). "Consistent with the public pan-cancer screening data, murine MLL-AF9 transformed AML cells showed a relevant gene-dependency only on Ybx1." (PMID 34465866, 2022). "Elevated expression of HOXC-AS3/YBX1/HOXC8 occurs in NSCLC cells, and inhibition of their expression significantly suppresses cancer cell proliferation, migration and invasion, resulting in attenuated tumour growth and metastasis in vivo." (PMID 35387975, 2022). "In future, the design and optimization of these oligonucleotide-based PROTACs, targeting oncogenic RBPs (e.g. IGF2BPs and YBX1) and DBPs (e.g. c-myc and STAT3), should be extensively investigated for targeted cancer therapy." (PMID 35410300, 2022). "Elevated YBX1 expression increased the transcription of HOXC8, as YBX1 bound to its promoter, leading to enhanced cancer cell proliferation, migration and invasion." (PMID 35387975, 2022). "Previous studies have demonstrated that some m5C regulators participate in the malignant progression of cancer such as NOP2 and YBX1." (PMID 34394351, 2021). "In the present study, Western blotting showed that cyclin B1 was attenuated by the downregulation of YBX-1 in HCT116, SUIT2 and OE33 cells, suggesting that YBX-1 also regulates the cell mitotic events in cancer cells." (PMID 34202873, 2021). "Of these 348 identified HOTAIR-interacting proteins, we selected YBX1, cyclin-dependent kinase 6 (CDK6) and translationally controlled tumor protein (TCTP), which are pivotal in cancer progression for additional validation." (PMID 34266873, 2021). "YBX1, an RBP belonging to the Y-box binding protein family, is abundantly expressed in many cancers." (PMID 34934044, 2021). "In cancer cells, the increased expression of HOTAIR allows this lncRNA to serve as a scaffold for the interaction of YBX1-pAKT and/or YBX1-pERK/pRSK, thereby leading to an increase in YBX1 S102 phosphorylation and subsequent nuclear translocation." (PMID 34266873, 2021). "In this study we were able to show a specific interaction between HOTAIR and YBX1, and we demonstrated that this interaction mediates at least in part the known effects of HOTAIR on cancer cell biology." (PMID 34266873, 2021). "Our study first reported the carcinogenic and cancer‐promoting effects of TMEM92‐AS1 in GC and showed that TMEM92‐AS1 regulated the expression of CCL5 by binding to YBX1 to exert function." (PMID 33247987, 2021). "Using Aurora A-as7 kinase, we have identified several direct targets, including PHLDA1, LIMK2, ALDH1A1, SPOP, YBX1, and TWIST1, in cancer cells." (PMID 34066036, 2021). "Recently, several studies also reported that YBX1 was involved in cell adhesion and mediated resistance to focal adhesion kinase (FAK) inhibitor in cancer." (PMID 31947823, 2020). "Taken together, our findings indicated that lncRNA HUMT promotes cancer cell proliferation, lymph node metastasis, and lymphangiogenesis by HUMT/YBX1/FOXK1-mediated Akt/mTOR and VEGFC signaling." (PMID 32138762, 2020). "The diverse biological functions of YBX1 and its involvement in cancer appear to arise not only from its broad nucleic acid binding properties, but may be dependent on its cooperativity with other signaling pathways and molecules responsible for cancer development and/or progression." (PMID 32985589, 2020). "Mechanistic investigations on SCAT7 in multiple cancer types using chromatin oligo-affinity precipitation (ChOP) and RNA immunoprecipitation (RIP) assays reveal that it interacts with the hnRNPK/YBX1 complex." (PMID 30658384, 2019).